MADD (MAP kinase activating death domain)
Diseases named in the same sentence as MADD in open-access papers (continued):
Sharing a sentence is not in itself a finding about the gene and the disease.
thyroid cancer (1 paper, 2018). "Further, MADD knock-down and/or MADD dephosphorylation can also render differentiated thyroid cancer cells susceptible to TRAIL." (PMID 30352606, 2018).
ulcers (1 paper, 2023). "This, accompanied by the high abundance of amyloid-beta precursor protein (APP), apolipoprotein E (APOE), MADD (MAP kinase-activating death domain protein), ATF6B, ERN1 and TRAP1 in the presence of ulcers, shows that, along with cell death, the epithelial health maintenance response is strong." (PMID 37170213, 2023).
cancer (11 papers, 2013 to 2025). A tumor composed of atypical neoplastic, often pleomorphic cells that invade other tissues. "Further, we have shown that treatment of cervical (HeLa), ovarian, (PA-1) and thyroid (WRO) cancer cells devoid of expression of the endogenous MADD are more susceptible to both spontaneous and TRAIL- and TNFα-induced apoptosis, primarily through the activation of the extrinsic apoptotic pathway." (PMID 23457619, 2013). "Studies regarding the role of DENN/MADD in human disease have mostly confirmed its pro-survival properties within the context of cancer." (PMID 28323882, 2017). "MADD is a cancer driver and it was shown before that expression of isoforms that skip exon 16 has anti-apoptotic effects." (PMID 27535130, 2016). "MADD is expressed at much higher levels in cancer cells and tissues relative to their normal counterparts." (PMID 23457619, 2013). "Map kinase Activating Death Domain containing protein (MADD), a splice variant of the IG20 gene, is essential for cancer cell survival and confers resistance to tumor necrosis factor-related apoptosis-inducing ligand (TRAIL) treatment." (PMID 23457619, 2013). "Previous studies from our laboratory that employed selective knockdown of IG20 splice variants using exon-specific shRNAs have shown that the MADD isoform of the IG20 gene is required and sufficient for cancer cell survival." (PMID 23457619, 2013). "Therefore, the ability of the exceptional RPs to activate the MADD signaling profile should be explored further as a mechanism of inducing sustained cancer death alone or in combination with other therapies." (PMID 40745386, 2025). "Therefore, knocking down MADD is likely to potentiate TRAIL-induced apoptosis selectively in cancer cells and significantly reduce the possibility of resistance development." (PMID 23457619, 2013). "However, in cancer cells where MADD is over-expressed, MADD binds to DR4 and DR5 and prevents FADD recruitment to the DRs." (PMID 23457619, 2013). "This process ultimately promotes tumor growth through the NCL/MADD/pERK axis, offering a new dimension to the activation of the MAPK signaling pathway in cancer progression." (PMID 39979245, 2025). "The Map kinase Activating Death Domain containing protein (MADD) isoform of the IG20 gene is over-expressed in different types of cancer tissues and cell lines and it functions as a negative regulator of apoptosis." (PMID 23457619, 2013). "The pro-survival role of MADD is limited to cancer cells and abrogation of MADD expression has no apparent effect on normal cell survival." (PMID 23457619, 2013).
tumor (10 papers, 2013 to 2025). "Next, we examined the PPHLN1 (exon 6, chr12:42778741–42778798) and MADD (exon 26, chr11:47330530–47330593) splicing patterns across a variety of tumour types (The Cancer Genome Atlas (TCGA)) and normal tissues (Genotype-Tissue Expression (GTEx))." (PMID 39025928, 2024). "Similar results were obtained following treatment of MB3W1 tumourspheres, as PPHLN1-Mo also significantly inhibits tumour properties, but MADD-Mo induces only a modest but significant increase in tumoursphere size." (PMID 39025928, 2024). "In addition, a reduction in proliferative index (Ki-67) and N-cadherin expression, and an increase in E-cadherin expression were observed in MADD siRNA-treated xenotransplanted tumour tissues." (PMID 33126409, 2020). "Likewise, in vivo MADD siRNA treatment also decreased lung metastases along with tumour regression." (PMID 33126409, 2020). "Collectively, these data confirmed that the tumor suppressor function of miR-3151 was mediated via downregulation of PIK3R2 and MADD." (PMID 26517243, 2015). "The phosphorylated AKT (p-AKT) can activate multiple downstream signaling molecules, inhibit tumor cell autophagy through mTOR, phosphorylate MADD, caspase-3, caspase-9, phosphorylate FOXO-1 to control the cell cycle, and promote tumor cell growth and/or metastasis." (PMID 37070074, 2023).
neurodevelopmental disorder (6 papers, 2021 to 2025). A behavioral and cognitive disorder with onset during the developmental period that involves impaired or aberrant development of intellectual, motor, or social functions. "MADD interacts with tumor necrosis factor alpha in activating the mitogen‐activated protein kinase pathway and has been associated with neurodevelopmental disorders." (PMID 40665476, 2025). "On the other hand, biallelic MADD variants cause a multisystemic neurodevelopmental disorder that includes sensorineural hearing loss in 17% of patients." (PMID 33924653, 2021). "Three patients harbored four predicted PL/P variants in other genes causing neurodevelopmental disorders (GRIN2B, MADD, TRPM3 and ZEB2), leading to alternative diagnoses for them." (PMID 38566815, 2024).
neurological diseases (3 papers, 2021 to 2025). "Regarding the overlapping genes MADD and GLO1 detected in the PWAS and TWAS analyses, previous studies found that they are not only associated with neurological diseases but also have a certain impact on neurological functions." (PMID 35893077, 2022). "Besides that, in this LD block, several variants act as eQTLs/sQTLs in the brain and whole blood, altering the expression of many genes already related to LOAD or other neurological diseases in human or animal studies, such as CELF1 itself, MADD, MYBPC3, NR1H3, NUP160, SPI1, and TOMM40." (PMID 34291080, 2021).
MADD also shares sentences with these, for which no sentence is quoted: infection (2 papers); Obesity (2); acute myeloid leukemia (1); amyotrophic lateral sclerosis (1); anaplastic thyroid cancer (1); autism (1); chronic lymphocytic leukemia (1); colon cancer (1); colorectal cancer (1); congenital heart disease (1); developmental delay (1); gastric cancer (1); head and neck cancer (1); hearing loss (1); hepatocellular carcinoma (1); Hypertension (1); immune diseases (1); Impaired glucose tolerance (1); Intellectual disability (1); Jaundice (1); Kleefstra syndrome 2 (1); language disorder (1); lung carcinoma (1); lymphoma (1); mental disorder (1); neuroblastoma (1); neurodegenerative disease (1); Neurodevelopmental delay (1); papillary thyroid cancer (1); Pitt-Hopkins syndrome (1).